NRAS (NRAS proto-oncogene, GTPase)
Diseases named in the same sentence as NRAS in open-access papers (continued):
Sharing a sentence is not in itself a finding about the gene and the disease.
lung carcinoma (98 papers, 2012 to 2025). "The aim of this study was to describe the clinicopathological features of lung carcinomas with NRAS mutations." (PMID 40423070, 2025). "Compared to lung cancer, NRAS mutations are more common in CRC, the percentage approximately 60% of mCRC, and are associated with strong aggressiveness." (PMID 39507527, 2024). "Notable examples include the presence of mutated KRAS, which has been associated with an unfavorable prognosis in pancreatic and lung cancer, as well as the presence of mutated NRAS, which has been related to a poor prognosis in metastatic melanoma." (PMID 38399367, 2024). "Our analysis revealed that regorafenib and tivozanib significantly improved the sensitivity in NRAS-mutated skin and lung cancers, respectively." (PMID 37863651, 2024). "Some other cancers including lung cancer, colon cancer, and neuroblastoma are also reported to carry NRAS mutations at a lower frequency." (PMID 37083947, 2023). "KRAS is the most frequently mutated isoform in lung cancer representing 19% of the cases, followed by NRAS (1%) and HRAS (< 1%)." (PMID 32962236, 2020). "For example lung cancer cell lines containing NRAS mutations have been shown to be sensitive to the MEK inhibitor selumetinib." (PMID 24956168, 2014). "This study shows that NRAS-mutated lung carcinoma may exhibit sarcomatoid features, rendering sarcomatoid features particularly important for detection." (PMID 40423070, 2025). "Our study was conducted using NGS platforms and is the first to show that NRAS-mutated lung carcinomas may exhibit sarcomatoid features." (PMID 40423070, 2025). "In addition, we proposed several FDA-approved cancer-targeted drugs for various cancer types through PRISM drug screens, such as cabazitaxel for VHL-mutated kidney cancer and alectinib for lung cancer with NRAS or KRAS mutations." (PMID 37863651, 2024). "For example, tamoxifen, an FDA-approved inhibitor of the protein kinase C genes PRKCB and PRKCE, currently used for breast cancer treatment, could potentially be used to target EGFR or KRAS-mutated lung cancers and NRAS-mutated skin cancer." (PMID 37863651, 2024). "To further support the idea of miR-708 as a precision medicine for NRAS mutation-driven cancers, we overexpressed miR-708 in breast cancer cells and lung cancer cells carrying KRAS mutation, MDA-MB-231 and A549, as well as normal lung epithelial cells, BEAS-2B." (PMID 37083947, 2023). "Several genes’ mutations were found to be a good prognostic marker for human cancer; examples include mutated KRAS that was correlated with poor prognosis of pancreatic and lung cancer and mutated NRAS that was correlated with poor prognosis of metastatic melanoma." (PMID 37033447, 2023). "Mutations in several genes were found to be good prognostic markers for human cancer; examples include mutated KRAS that was correlated with a poor prognosis of pancreatic and lung cancer, and mutated NRAS that was associated with a poor prognosis of metastatic melanoma." (PMID 36430577, 2022). "Moreover, the combination of smoking and environmental carcinogens can be associated with the etiology of NRAS mutated lung cancer." (PMID 28097440, 2017). "Our study provides evidence that NRAS mutant cancers share similarities in their signaling behavior, which allows the conclusion that MEKi and PI3K/mTORi might also be effective in other malignancies which bear NRAS mutations, including neuroblastoma and lung cancer." (PMID 25277205, 2014). "For example, in FGFR inhibitor-resistant lung cancer cells, NRAS amplification and DUSP6 deletion resulted in mitogen-activated protein kinase (MAPK, i.e., ERK) reactivation." (PMID 40076427, 2025).
lung carcinoma (continued). "For other prevalent actionable mutation in lung cancer KRAS, PIK3CA, FGFR3, MET, NRAS, and RET demonstrated 100 % specificity with varied sensitivities around 50 %." (PMID 40503459, 2025). "For establishing the causal connection between DHA-mediated inhibition of the NRAS signaling pathway and the anti-proliferation effect from DHA, then NRAS over-expression was conducted in lung cancer cells." (PMID 38778121, 2024). "The following experiments revealed that the DHA’s effects on the NRAS signaling pathway, DNA damage, and proliferation ability of lung cancer cells." (PMID 38778121, 2024). "Transcriptome expression analysis from the GEPIA showed lung cancer tissues also exhibited higher NRAS, Cdc25a, CDK4, and γ-H2A.X expression." (PMID 38778121, 2024). "DHA enhances DNA damage by inhibiting the NRAS signaling pathway in lung cancer cells is still enclosed." (PMID 38778121, 2024). "On the contrary, those G-proteins, such as RAB5A, HRAS, and NRAS, that are modified either by two polyisoprenyl groups or a polyisoprenyl group and lipid thioester were relatively unaffected in lung cancer A549 and NCI-H1299 cells." (PMID 38540084, 2024). "As reported, the expression of the NRAS was lower in normal lung cells, but significantly higher in lung cancer cells." (PMID 38778121, 2024). "The Downward group has reported several murine KRASG12C-driven lung cancer cell lines including an NRAS-deleted derivative of the LLC model as well as KPARG12C and KPB6G12C cells that exhibit varying degrees of in vivo sensitivity to KRASG12C inhibitors." (PMID 36845684, 2023). "In our study, MEK and mTORC1/2 inhibitors exhibited a synergistic effect in 4 out of 5 NRAS mutant lung cancer cell lines." (PMID 32191822, 2021). "Three cell lines, including H1299 (lung cancer), A549 (lung cancer), and T24 (bladder cancer), harboring the NRAS, KRAS, and HRAS oncogene, resp., were transfected with the PY4- -Luciferase and Ranila plasmids." (PMID 34172933, 2021). "Our study involved several lung cancer models including H1975 (EGFR mutations), A549 (KRAS mutation), and H1299 (NRAS mutation)." (PMID 33214553, 2020). "It is also worth noting that LCAT1 was upregulated in a distinct subgroup of lung cancer patients that don’t have actionable mutations in EGFR, ALK, ROS or NRAS." (PMID 31779616, 2019). "Recently, reactivation of MAPK pathway, mediated by NRAS amplification or MET transcriptional regulation, has been linked to the emergence of resistance to FGFR inhibitors in FGFR1-amplified lung cancer cell models." (PMID 30972293, 2019). "We have found that KEAP1 loss modulates sensitivity to inhibition of EGFR, ALK, BRAF, or MEK in lung cancer cell lines with EGFR, ALK, BRAF, KRAS, or NRAS mutations." (PMID 28145866, 2017). "In summary, particular NRAS, AKT1 and PTEN gene mutations occur with similar rare (~1%) frequency in CNS metastases of NSCLC as in primary lung cancer tumors." (PMID 28097440, 2017). "The frequency of PIK3CA, NRAS, HRAS, and PTEN mutations was higher in cfDNA than in lung cancer tissue in the cBioPortal database." (PMID 29290998, 2017). "We and others have shown that NRAS mutations sensitize towards inhibition of MEK in cutaneous T-cell lymphoma, lung cancer and neuroblastoma cell lines." (PMID 26821351, 2016). "Other studies in NRAS mutant lung cancer cell lines support our findings, albeit in different cell lines." (PMID 25277205, 2014). "A study recently reported on the clinical characteristics of NRAS mutant lung cancer, which accounts for approximately 1% of non-small cell lung cancers." (PMID 25277205, 2014). "Neuroblastoma cells tended to be more sensitive to NRAS knockdown than lung carcinoma cells, still all NRASQ61 mutated cell lines proved to be dependent on NRAS signaling for cell homeostasis." (PMID 25277205, 2014).
lung carcinoma (continued). "There are further reports that downregulation of this cluster marks early relapse in advanced stage ovarian cancer patients and expression of miR-506 inhibits NRAS expression and suppress growth and tumorigenesis in a lung cancer model." (PMID 23748164, 2013). "In H1299 lung cancer cells, which contain a mutant NRAS gene, LOX-PP reduced the activation of ERK and Akt, and ability for anchorage-independent growth and invasive colony formation in Matrigel." (PMID 22438909, 2012). "Consequently, all of these data recommended that DHA-mediated anti-lung cancer effect through blocking NRAS signaling and thereby inducing DNA damage." (PMID 38778121, 2024). "Moreover, not only the DNA damage was impaired, but the proliferation of lung cancer cells was also revitalized while NRAS was over-expression." (PMID 38778121, 2024). "We postulated whether its selective anti-lung cancer effect might be attributed to its action on NRAS signaling." (PMID 38778121, 2024). "In this case, the NRAS mutation was predominantly identified, the most common gene mutations in lung cancer are all negative, including EGFR, KRAS, BRAF, ALK, ROS1, and so on." (PMID 39507527, 2024). "Notably, NOP56 silencing also inhibited NRAS-mutant lung cancer H1299 cells, although the effects on EGFR-mutant (EBC-1) or FGFR1-amplified (H520) lung cancer cells were negligible." (PMID 35039048, 2022). "Finally, we identified a potential combination of EGFR and MEK-targeted therapies as a possible treatment option for patients with EGFR-driven lung cancer with NRAS gene amplification as a bypass signaling pathway." (PMID 34642436, 2021). "We observed heterogeneity in response to MEK inhibitors in five NRAS mutant lung cancer cell lines." (PMID 32191822, 2021). "Our data show that NRAS is also involved in the response of lung cancer cells to external electric field stimulation, suggesting that NRAS may also anticipate in the electrochemical treatment of tumors." (PMID 32210363, 2020). "We analyzed the Variant Caller Files generated by bioinformatics analyses and we retained all non-synonymous and splice variants found at 1% with at least 50 mutated reads both for KRAS/NRAS-positive and negative colon and lung cancer biopsies." (PMID 29765524, 2018). "NRAS is overexpressed in lung cancer cells and can be directly downregulated by miR-515-5p." (PMID 27556696, 2016). "This indicates the potential use of those inhibitors in NRAS mutant lung cancer and neuroblastoma." (PMID 25277205, 2014). "Among the different tumors which are known to harbor NRAS mutations, we decided to focus our experiments on lung cancer and neuroblastoma cell lines, due to the lack of studies in this specific subset of cells." (PMID 25277205, 2014). "Finally, we included 10 well-known cancer-related genes (or their hotspot-containing exons) listed as most frequently mutated in lung cancer (BRAF,EGFR,ERBB2,HRAS,KRAS,MAP2K1,MET,NF1,NRAS, and RIT1) in the panel to serve as internal controls for highly mutated regions." (PMID 40867048, 2025). "The results showed expression of Ki67 and PCNA revitalized with the treatment of DHA and NRAS plasmid compared with DHA treatment alone, suggesting that recovery of NRAS molecule abolished DHA-driven anti-lung cancer proliferation." (PMID 38778121, 2024). "The SHC1, FKBP4, NRAS, and KRAS had higher expressions in lung cancer tissues compared with lung normal tissues in LUAD." (PMID 33936178, 2021). "The titer of autoantibodies against MFGE8, NRAS, PTP4A1, RRAS2 was measured in serum of 80 esophagus cancer cases (ECs), 80 hepatocellular carcinoma cases (HCCs), 80 lung cancer cases (LCs), and 80 healthy controls by ELISA." (PMID 33718231, 2021).
lung carcinoma (continued). "Loss of KEAP1, a negative regulator of NFE2L2/NRF2, modulated the response to BRAF, MEK, EGFR, and ALK inhibition in BRAF-, NRAS-, KRAS-, EGFR-, and ALK-mutant lung cancer cells." (PMID 28145866, 2017). "Our panel included 22 genes, although the approved predictive biomarkers in colon and lung cancer are quite few (KRAS, NRAS, EGFR, ALK)." (PMID 25637035, 2015). "Higher NRAS, p-ERK1/2, and Cdc25a expression could be observed in LLC and A549, confirming that the NRAS signaling pathway was activated in lung cancer cells." (PMID 38778121, 2024). "In the first set, we performed three genome scale screens with the MEK inhibitor trametinib, in the NRAS-mutant lung cancer cell line H1299 (NRASQ61K), the BRAF-mutant lung cancer cell line HCC364 (BRAFV600E), and the KRAS-mutant lung cancer cell line CALU1 (KRASG12C)." (PMID 28145866, 2017). "5/6 NRAS mutant lung cancer cell lines were sensitive to single-agent selumetinib and MEK signalling appeared to be significantly more important than PI3K/AKT activation given the lack of effect of GDC-0941 in these NRAS mutant lung cancer cell lines." (PMID 26410619, 2015). "Taken together, DHA could induce selective anti-lung cancer efficacy through binding to EGFR and thereby abolishing the NRAS signaling pathway, thus leading to DNA damage, which provides a novel theoretical basis for phytomedicine molecular therapy of malignant tumors." (PMID 38778121, 2024). "Interestingly, LCAT1 was upregulated in a distinct subgroup of lung cancer patients who did not have actionable mutations in EGFR, ALK, ROS or NRAS." (PMID 31779616, 2019). "For metastatic colorectal and lung cancer patients, where treatment with anti-EGFR monoclonal antibodies is only effective in patients whose tumours are RAS wild type, sequencing 3 exons of KRAS and 3 exons of NRAS is required, and this will possibly also be the case for other tumour types shortly." (PMID 26919633, 2016). "Taken together, these findings were crucial evidence that DHA could impair the NRAS signaling pathway, thereby promoting DNA damage and arresting the cell cycle, which may be the mechanism by which DHA exhibited a selective anti-proliferation effect in lung cancer cells." (PMID 38778121, 2024).
metastatic melanoma (94 papers, 2005 to 2025). A melanoma that has spread from its primary site to another anatomic site. "The somatic mutation in the NRAS oncogene was reported in 28% of primary and metastatic melanoma; NRAS encodes GTP-binding proteins located upstream of the BRAF within the MAPK pathway." (PMID 40867317, 2025). "In conclusion, we reviewed metastatic melanoma’s genetic and biological properties, highlighting the significance of molecular mutations like NRAS, BRAF, NF1, and others in disease progression and treatment responses." (PMID 38534309, 2024). "Previous studies suggested that somatic BRAF and NRAS mutations in metastatic melanoma increase the risk for brain metastases." (PMID 38339344, 2024). "In metastatic melanoma patients who lack BRAF V600E mutations (including patients with NRAS and NF1 mutation), targeted therapy has shown minimal effectiveness." (PMID 37444637, 2023). "An earlier study in metastatic malignant melanoma has shown that a patient harboring NRAS-activating mutation exhibited disease stabilization for 49months following administration of pharmacologically active doses of 17-AAG." (PMID 35264575, 2022). "Our results revealed for the first time that the upregulation of PLA1A in the serum of advanced metastatic melanoma tissues represent an excellent diagnostic marker in BRAF/NRAS-driven melanomagenesis." (PMID 33723350, 2021). "It would now be of great interest to evaluate the possible association between these SL metabolic alterations and the mutation status of oncogenes such as BRAF or NRAS as well as immune responses in metastatic melanoma patients." (PMID 32858889, 2020). "In one report, a patient with triple wild-type (BRAF/NRAS/NF1 WT) metastatic melanoma with two missense mutations in MAP2K1 showed a partial response to MEK inhibitor trametinib, followed by progression of disease after two months." (PMID 32483240, 2020). "This study focuses on the management of patients with mCRC, but KRAS, NRAS or BRAF mutations testing is also relevant in other cancers like metastatic melanoma or non-small cell lung cancer." (PMID 30811471, 2019). "Relatively frequent IDH1 mutations (4.9%) were detected also in metastatic melanoma associated with NRAS mutation." (PMID 31745173, 2019). "Ten patients with metastatic melanoma with established driver BRAF or NRAS mutations were included in this study; 5/10 patients were aged 65 years or older, 8/10 were male and 6/10 had American Joint Committee on Cancer (AJCC) stage M1c disease." (PMID 31795494, 2019). "The mutated BRAF oncogene represents a therapeutic target in metastatic melanoma, where a mutated NRAS oncogene is a biomarker of poor outcome and resistance to treatment with BRAF inhibitors." (PMID 30546839, 2018). "We investigated the feasibility of the IdyllaTM assay for detection of BRAF and NRAS mutations in cfDNA of 19 patients with metastatic melanoma at baseline and during the course of treatment." (PMID 30546839, 2018). "In this study, we evaluated the fully automated ready-to-use IdyllaTM PCR-based system for identification of BRAF V600 and NRAS mutations in plasma samples from patients with metastatic melanoma at baseline and during the course of treatment." (PMID 30546839, 2018). "The mutation status of the BRAF and NRAS genes in tumor tissue is used to select patients with metastatic melanoma for targeted therapy." (PMID 30546839, 2018). "A quite similar frequency of either BRAF or NRAS mutations was observed among primary and metastatic melanomas: 49% vs. 51%, for BRAF, and 15% vs. 16%, for NRAS, respectively." (PMID 23987572, 2013). "Activating mutations in the BRAF (V600E) and NRAS (Q61K) genes are found at a frequency of 40–60 and 15–30 % in metastatic melanomas, respectively." (PMID 23673558, 2013). "Similar results were obtained in the SK-Mel 30, another NRAS-mutated metastatic melanoma cell line." (PMID 35371312, 2022).